INSRR (insulin receptor related receptor)
Description:
Receptor with tyrosine-protein kinase activity. Functions as a pH sensing receptor which is activated by increased extracellular pH. Activates an intracellular signaling pathway that involves IRS1 and AKT1/PKB.
Synonyms: IRR
Tractability: Small molecule: a high-quality ligand is known; it belongs to a druggable protein family. Antibody: UniProt predicts a signal peptide or a membrane-spanning region; its Gene Ontology location is reachable by antibodies, with medium confidence. PROTAC: ubiquitination databases record sites on it; a small molecule that binds it is known.
Target class: Enzyme; Tyrosine protein kinase InsR family; TK protein kinase group; Kinase; Protein Kinase
Chemical probes: linsitinib (high quality)
Safety:
Unwanted effects reported when the protein is acted on. In parentheses: how it was acted on, where the effect was seen, and who reports it.
require glucarpidase treatment (source: ClinPGx)
Gene: Protein-coding gene on chromosome 1 (156,840,063 to 156,859,117, reverse strand). Ensembl gene ENSG00000027644.
Subcellular location: Membrane
Gene Ontology:
Molecular function: protein binding; transmembrane receptor protein tyrosine kinase activity; insulin receptor activity; ATP binding; insulin receptor substrate binding; phosphatidylinositol 3-kinase binding; protein kinase activity; protein tyrosine kinase activity
Biological process: actin cytoskeleton organization; cellular response to alkaline pH; cell surface receptor protein tyrosine kinase signaling pathway; insulin receptor signaling pathway
Cellular component: receptor complex; axon; insulin receptor complex; plasma membrane; membrane
Genetic constraint (gnomAD): Loss-of-function variants: 118 observed, 135.77 expected, observed/expected ratio (o/e) 0.87, 90% interval 0.75 to 1.01. The upper end of that interval is the gene's LOEUF score, 1.01, which puts it in group 4 of 6, group 1 being the genes least tolerant of losing a copy. Missense variants: 1,657 observed, 1,804.4 expected, observed/expected ratio (o/e) 0.92, 90% interval 0.88 to 0.96. Synonymous variants: 674 observed, 739.34 expected, observed/expected ratio (o/e) 0.91, 90% interval 0.86 to 0.97.
Homologues: Orthologues: chimpanzee INSRR (99% identical), macaque INSRR (99% identical), rabbit INSRR (93% identical), pig INSRR (93% identical), dog INSRR (93% identical), guinea pig INSRR (90% identical), rat Insrr (89% identical), mouse Insrr (89% identical), tropical clawed frog insrr (65% identical). Paralogues in human: IGF1R (56% identical), INSR (53% identical), ROS1 (19% identical), ALK (16% identical), NTRK3 (15% identical), MET (15% identical), NTRK2 (15% identical), NTRK1 (15% identical), ERBB2 (15% identical), ERBB4 (15% identical), EGFR (14% identical), TIE1 (14% identical), and 41 more.
Diseases named in the same sentence as INSRR in open-access papers:
INSRR is named in the same sentence as 11 diseases in open-access papers, as found by Europe PMC text mining. Sharing a sentence is not in itself a finding about the gene and the disease. The quoted sentences say what the papers report.
breast carcinoma (2 papers, 2013 to 2023). "TEX14 has been implicated in multiple myeloma and breast cancer, and INSRR has been implicated in ovarian epithelial cancers and neuroblastomas." (PMID 23826350, 2013). "Several studies have shown that INSRR is an insulin receptor-related protein that can enhance the proliferation of several human breast cancer cell lines, possibly because of its synergistic effect with estrogen and insulin-like growth factor (IGF)." (PMID 37168445, 2023).
Insulin resistance (2 papers, 2017 to 2021). Increased resistance towards insulin, that is, diminished effectiveness of insulin in reducing blood glucose levels. "Similarly, we observed that SOS2 was another seeder gene that was linked with SRC, INSRR, EGFR, FGFR1, PGFRA and PGFRB gene signatures that were significantly associated with insulin resistance and type 2 diabetes." (PMID 28179884, 2017).
cancer (3 papers, 2021 to 2023). A tumor composed of atypical neoplastic, often pleomorphic cells that invade other tissues. "Other genes include immune responses of T cells in cancer cells, insulin-receptor-related protein (INSRR), MHC II complex HLA-DQB and HLA-DQA, IL-12A, IL-20, glucose transporter 4 (GLUT4), insulinoma-associated protein 1 (INSM1), and insulin receptor (INSR)." (PMID 36769056, 2023). "Notably, TIE1, KIT, NTRK1, FGFR3, CSF1R, and INSRR were shared by both cancers." (PMID 34944663, 2021).
tumor (2 papers, 2021). "Furthermore, overexpression of FGF12, FGF14, FGF17, FGFR1, FGFBP3 and IGFBPL1 genes was found in early tumor stage, while, overexpression of IGF1R, IGF2BP2 and INSRR was found in advanced tumor stages." (PMID 34061869, 2021). "INSRR is considered as a tumor endothelial marker and its overexpression can promote angiogenesis." (PMID 34744717, 2021).
INSRR also shares sentences with these, for which no sentence is quoted: neuroblastoma (2 papers); type 2 diabetes (2); Alkalosis (1); cataract (1); glioma (1); multiple myeloma (1); soft tissue neoplasm (1).